KERA (keratocan)
Description:
May be important in developing and maintaining corneal transparency and for the structure of the stromal matrix.
Synonyms: KTN; SLRR2B; CNA2
Tractability: Antibody: its Gene Ontology location is reachable by antibodies, with high confidence; UniProt places it where antibodies can reach, with medium confidence; UniProt predicts a signal peptide or a membrane-spanning region.
Gene: Protein-coding gene on chromosome 12 (91,050,491 to 91,058,024, reverse strand). Ensembl gene ENSG00000139330.
Subcellular location: Secreted, extracellular space, extracellular matrix
Pathways (Reactome):
Disease: Defective B4GALT1 causes B4GALT1-CDG (CDG-2d); Defective CHST6 causes MCDC1; Defective ST3GAL3 causes MCT12 and EIEE15
Metabolism: Keratan sulfate biosynthesis; Keratan sulfate degradation
Gene Ontology:
Cellular component: extracellular matrix; extracellular region; gel phase of interstitial matrix; Golgi lumen; lysosomal lumen
Genetic constraint (gnomAD): Loss-of-function variants: 24 observed, 26.28 expected, observed/expected ratio (o/e) 0.91, 90% interval 0.66 to 1.28. The upper end of that interval is the gene's LOEUF score, 1.28, which puts it in group 5 of 6, group 1 being the genes least tolerant of losing a copy. Missense variants: 415 observed, 410.22 expected, observed/expected ratio (o/e) 1.01, 90% interval 0.93 to 1.1. Synonymous variants: 155 observed, 147.51 expected, observed/expected ratio (o/e) 1.05, 90% interval 0.92 to 1.2.
Homologues: Orthologues: chimpanzee KERA (99% identical), macaque KERA (99% identical), dog KERA (92% identical), pig KERA (91% identical), rabbit KERA (90% identical), rat Kera (86% identical), mouse Kera (86% identical), guinea pig KERA (84% identical), tropical clawed frog kera (57% identical), zebrafish kera (55% identical). Paralogues in human: PRELP (52% identical), OMD (39% identical), FMOD (38% identical), LUM (35% identical), ECM2 (30% identical), LINGO3 (20% identical), LINGO4 (19% identical), OMG (18% identical), EPYC (18% identical), OGN (17% identical).
Diseases named in the same sentence as KERA in open-access papers:
KERA is named in the same sentence as 28 diseases in open-access papers, as found by Europe PMC text mining. Sharing a sentence is not in itself a finding about the gene and the disease. The quoted sentences say what the papers report.
cornea plana (6 papers, 2005 to 2020). A rare developmental defect of the eye characterized by usually bilateral absence of the normal protrusion of the cornea from the sclera, the corneal curvature being the same as that of the adjacent sclera. "In fact, mutations in the KERA gene have been associated with the more severe forms of cornea plana." (PMID 32903857, 2020). "In this report, we present the clinical data and describe a new KERA mutation in a Turkish family with autosomal recessive cornea plana." (PMID 26099342, 2015). "Interestingly, mutations in the keratocan gene leading to a single amino acid substitution or a C-terminal truncation cause flattening of the anterior corneal curvature in humans, a condition called cornea plana." (PMID 32903857, 2020). "Alternatively, the child with the large interstitial deletion may actually have autosomal recessive cornea plana with unmasking of a recessive allele, a possibility that was not excluded as KERA was not screened." (PMID 24759697, 2014). "The absence of opthalmic effects in the assumed GOF mutation carriers is in line with previous studies, showing that KERA mutations are not identified in subjects suffering from cornea plane type 1 (CP1), the autosomal dominant form of cornea plana." (PMID 24879339, 2014).
keratoconus (3 papers, 2005 to 2018). A degenerative, structural disorder of the eye, characterized by a cone-shaped protrusion of the cornea. "The expression of stromal proteins such as vimentin, decorin and keratocan was reported to increase following keratoconus surgery." (PMID 27473120, 2016).
cornea plana 2 (2 papers, 2014 to 2018). Any cornea plana in which the cause of the disease is a mutation in the KERA gene. "Autosomal recessive LOF mutations in KERA cause cornea plana type 2 (CP2), an ophthalmologic disorder characterised by corneal flattening, but split lamp examination in 2 carriers of the KERA p.Ser307Cys mutation did not reveal CP2 characteristics." (PMID 24879339, 2014). "For the CCT loci identified here, DCN (12 kb from rs7308752) and KERA in the same locus (75 kb from rs7308752), are involved in congenital stromal corneal dystrophy (OMIM: 610048) and Cornea plana 2 (OMIM:217300), respectively." (PMID 29760442, 2018).
Hyperglycemia (2 papers, 2018 to 2019). An increased concentration of glucose in the blood. "Results demonstrated successful differentiation of hCSSCs into keratocytes with KERA and LUM genes being highly expressed and only modest effects of hyperglycemia on collagen or proteoglycan expression." (PMID 30470798, 2018).
posterior amorphous corneal dystrophy (2 papers, 2011 to 2022). Posterior amorphous corneal dystrophy (PACD) is a very rare form of stromal corneal dystrophy characterized by irregular amorphous sheet-like opacities in the posterior corneal stroma and in Descemet membrane and mildly impaired vision. "A human genome-wide linkage analysis of posterior amorphous corneal dystrophy identified a region of human chromosome 12 that is orthologous to a Mcs6 region that contains genes DCN, LUM, KERA, and EPYC." (PMID 21625632, 2011).
albinism (1 paper, 2020). A congenital disorder characterized by partial or complete absence of melanin pigment in the eyes, hair, or skin. "The genes identified for MAC were KMT2D, MAB2IL2, ALDH1A3; ASDA were KERA, PAX6, MYOC, TGFBI, and SLC4A11; congenital cataract were CRYBB2, EPHA2, HSF4 and BCOR; infantile nystagmus were CACNA1A and FRMD7; and albinism were OCA2, GPR143, HPS6 and SLC38A8." (PMID 32830442, 2020).
atherosclerosis (1 paper, 2014). A disease characterized by the build-up of fatty material and calcium deposition in the arterial wall resulting in partial or complete occlusion of the arterial lumen. "We identified a novel p.Ser307Cys mutation in the extracellular matrix protein KERA in a large pedigree with a Mendelian form of premature atherosclerosis by linkage analysis combined with next generation sequencing." (PMID 24879339, 2014). "Next we tested whether KERA protein expression was associated with atherosclerotic burden in an established Apoe−/− mouse model for atherosclerosis, in which atherosclerosis was induced by perivascular collar placement." (PMID 24879339, 2014). "A rare variant in KERA was identified in a large kindred with premature atherosclerosis." (PMID 24879339, 2014). "Interestingly, the protein was absent from healthy artery segments, but heavily abundant within the lipid core of atherosclerotic lesions, which emphasizes that KERA might be a novel actor in the pathobiology underlying atherosclerosis." (PMID 24879339, 2014). "Although the results from this study are suggestive of a role for KERA in atherosclerosis, a direct causative role has not been established thus far." (PMID 24879339, 2014). "A specific concern is that neither we, nor others did observe possible KERA GOF mutations in other cases with premature atherosclerosis." (PMID 24879339, 2014). "An increased risk for atherosclerosis has not been reported in these individuals, but this might have been overlooked because previous studies may have focussed solely on the ophthalmological consequences of KERA mutations." (PMID 24879339, 2014). "The role of KERA in atherosclerosis has not been investigated so far, but it is interesting to note that KERA has been shown to play a role in neutrophil migration." (PMID 24879339, 2014). "Additionally we have tested arterial segments from 9 patients at different stages of atherosclerosis progression and found that KERA was not expressed in 2 non-diseased arterial segments but was expressed in atherosclerotic plaque regions." (PMID 24879339, 2014).
Fuchs' corneal dystrophy (1 paper, 2017). "Lumican and keratocan have been shown to be significantly decreased in KC, yet keratocan has been reported to be highly expressed in the stroma of KC compared to normal or other diseased cornea samples, such as from Fuchs' corneal dystrophy or pseudophakic bullous keratopathy patients." (PMID 28251158, 2017).
keratitis (1 paper, 2013). A corneal disease that is characterized by inflammation of the cornea. "Similarly, CXCL1 levels in the sterile LPS-keratitis model was reportedly increased in the anterior chamber of mice deficient in lumican and keratocan, another corneal proteoglycan." (PMID 23358433, 2013).
microphthalmia (1 paper, 2020). Congenital or developmental anomaly in which the eyeballs are abnormally small. "Similarly, family 17 had unilateral left microphthalmia with cornea plana, anterior segment dysgenesis, left exotropia and high hypermetropia, and was identified to have a homozygous missense variant (c.809C>T, p.[Ser270Leu]) in the KERA gene (OMIM #603288)." (PMID 32830442, 2020).
osteoporosis (1 paper, 2025). A condition of reduced bone mass, with decreased cortical thickness and a decrease in the number and size of the trabeculae of cancellous bone (but normal chemical composition), resulting in increased fracture incidence. "Our bioinformatics analyses showed that keratocan expression was reduced in the muscles of sarcopenia mice and the bones of osteoporosis mice, suggesting that keratocan may be a common protective gene." (PMID 39962589, 2025).
sarcopenia (1 paper, 2025). Progressive decline in muscle mass due to aging which results in decreased functional capacity of muscles. "We found that keratocan expression was reduced in the bones of osteoporotic mice and in the muscles of sarcopenic mice, which is consistent with the results of previous studies; however, the role of keratocan in sarcopenia has not yet been reported." (PMID 39962589, 2025).
stromal corneal dystrophies (1 paper, 2023). "The corneal stroma, on the other hand, was found to be composed of classic keratocyte markers, keratocan (KERA), lumican (LUM), and decorin (DCN), all of which are associated with stromal corneal dystrophies." (PMID 37138096, 2023).
tumor (3 papers, 2016 to 2023). "The presence of transcripts for FMOD, PRELP and OMD was widespread in the patients analyzed, while expression of LUM and KERA was detected in only around 50% of cases in both healthy and tumor tissue." (PMID 34440771, 2021). "Lastly, three genes (TBC1D12, KERA, and TUBA3D) that contribute to tumor clustering in groups “0” and “1” have not been previously associated with the tumor-related autophagy process." (PMID 37628602, 2023). "Other differences were also detected between the two types of tumor, specifically the lack of expression of KERA and the appearance of certain levels of PODNL1, but in both cases these alterations were limited to some patients." (PMID 34440771, 2021). "Transcripts for the five genes encoding class II SLRPs (FMOD, LUM, PRELP, KERA and OMD) were quantified in both healthy and tumor tissue, with no significant expression differences between tissue type." (PMID 34440771, 2021). "Interestingly, we also discovered three genes (TBC1D12, KERA, and TUBA3D) that have not been previously associated with tumor-related autophagy." (PMID 37628602, 2023).
KERA also shares sentences with these, for which no sentence is quoted: connective tissue diseases (2 papers); Axenfeld-Rieger syndrome type 3 (1); Blindness (1); cancer (1); congenital cataract (1); congenital glaucoma (1); congenital stromal corneal dystrophy (1); corneal disorder (1); corneal dystrophies (1); Corneal opacity (1); hyperopia (1); Loeys-Dietz syndrome (1); mastitis (1); myopia (1).